TERT (telomerase reverse transcriptase)
Diseases named in the same sentence as TERT in open-access papers (continued):
Sharing a sentence is not in itself a finding about the gene and the disease.
cancer (continued). "Based on the data from all 32 studies, we found a significant increased cancer risk for the TERT rs2853676 A allele under a per-allele risk analysis (OR = 1.08, 95% CI = 1.04–1.13, p < 0.001), with a statistical power of 100%." (PMID 26042809, 2015). "After TERT promoter mutations, this report constitutes only a second instance of highly frequent mutations being reported in human cancers within the non-coding regulatory sequences that have been called as the ‘dark matter’ of the genome." (PMID 26416425, 2015). "Reverting the mutation in the TERT promoter decreases telomerase levels and telomere length, and thereby limits the growth of these cancer cells." (PMID 26553065, 2015). "Multiple cancer-associated single nucleotide polymorphisms (SNPs) associated with risk of a wide variety of cancers have been identified in the TERT-CLPTM1L region of 5p15.33, identifying this as a multi-cancer susceptibility locus." (PMID 26053551, 2015). "A growing number of epidemiological studies have been conducted in response, which have provided evidence that TERT polymorphisms contribute to cancer development." (PMID 26042809, 2015). "In molecular epidemiology studies, several TERT polymorphisms have been reported to be associated with the risk of many cancer types." (PMID 26020272, 2015). "The first and arguably most significant discovery of somatic cis-regulatory mutations in cancer were recurrent somatic mutations found in the promoter of the telomerase reverse transcriptase (TERT) gene." (PMID 26356674, 2015). "Recent studies of various human cancer genomes have identified two highly recurrent TERT promoter mutations (C-124T and C-146T), which generate new binding sites for the ETS transcription factor GABP." (PMID 26553065, 2015). "Here we address these questions by genetically engineering human embryonic stem cells (hESCs) to carry the three most prevalent cancer-associated TERT promoter mutations in an isogenic background." (PMID 26194807, 2015). "We also corrected a cancer-associated TERT promoter mutation in a urothelial cancer cell line and showed that the telomerase level and growth rate of these cancer cells were decreased." (PMID 26553065, 2015). "This seminal finding represented the first identification of recurrent somatic mutations within a promoter region in cancer and has led to further studies aimed at determining the prevalence of TERT promoter mutations in other cancers." (PMID 26356674, 2015). "While the point mutations tend to associate with higher TERT expression, most of the six ChRCC cases with promoter-associated structural variants (SVs) appear even higher than most cancers with the mutation." (PMID 25859550, 2015). "Only a few studies have paid attention to the associations between TERT variants and cancer progression, whereas the findings have remained controversial." (PMID 26020272, 2015). "For instance, two point mutations in the promoter region of the human TERT gene (C-124T and C-146T) have been reported to be highly recurrent in various cancers types and correlate with higher telomerase levels." (PMID 26553065, 2015). "In 2013, two articles were published simultaneously that documented independent discoveries of cancer-associated variation within the TERT promoter." (PMID 26356674, 2015). "Accordingly, TERT promoter mutations belong to the most common somatic genetic lesions in human cancers." (PMID 24726063, 2014). "The identification of recurrent TERT promoter mutations in human malignancies has significantly contributed to the understanding of the cancer-specific TERT expression." (PMID 25474136, 2014). "Likely, the promoter mutation-induced TERT expression provides cancer cells with a proliferation advantage by stabilizing telomere size." (PMID 25474136, 2014). "Surrogate SNPs in linkage disequilibrium with the majority of cancer-associated SNPs were functional variants with a likely role in regulation of TERT and/orCLPTM1L." (PMID 26664699, 2014).
cancer (continued). "More recently, point mutations have been found in the promoter region of TERT in multiple types of cancer, leading to higher TERT mRNA expression." (PMID 25159915, 2014). "It has also been shown that certain single nucleotide polymorphisms increase cancer risk by up-regulating TERT expression and telomerase activity." (PMID 25301727, 2014). "TERT rs2736100_C was previously shown to also associate with elevated risk for several other cancers, albeit with lower effect 25–28." (PMID 25196853, 2014). "Recent studies have demonstrated a transcriptional activation role for the TERT promoter mutations C228T and C250T in many human cancers, as well as a role in aggressive disease with potential clinical applications." (PMID 24803525, 2014). "Previous studies showed that TERT promoter mutations are frequent in familial and sporadic melanoma and other cancer types." (PMID 25393105, 2014). "Located in the TERT-CLPTM1L region at 5p15.33 harboring multiple variants that are associated with susceptibility to many types of human cancer, the variant rs401681T allele is associated with increased risk for death of SCLC in this study." (PMID 25415319, 2014). "Recurrent HBV integrations near cancer-related genes like TERT indicate that HBV can play a causal role in HCC." (PMID 25159915, 2014). "The recently described mutations in the promoter region of TERT provide new evidence for the important role of telomerase reactivation in human cancers." (PMID 24726063, 2014). "Immortalisation is a hallmark of cancer commonly achieved by transcriptional reactivation of the telomerase reverse transcriptase gene TERT." (PMID 24550717, 2014). "These incidences of TERT promoter mutations in SCC of different origins are concord with those counterpart usual carcinomas." (PMID 25042800, 2014). "We show that allelic variants of rs7736074 and rs4975596 modulate TERT expression levels in multiple cancer types, and exhibit preliminary prognostic value for response to cetuximab." (PMID 24152305, 2013). "TERT promoter mutations were also found in a number of other common cancers, including hepatocellular cancer, bladder cancer, thyroid cancer and gliomas." (PMID 24260374, 2013). "Recently, there are several reports which show that polymorphisms in the hTERT gene and in TERT-CLPTM1L locus are associated with the risks of various cancer types." (PMID 23762817, 2013). "Among the genes in skin with a significant GxA interaction we found 31 genes associated with cancer, including the Telomerase reverse transcriptase (TERT), which is also involved in aging via its effect on telomere length." (PMID 23889843, 2013). "The telomerase and telomerase reverse transcriptase (TERT) constitute an essential component of the telomerase complex which role is also implicated in the etiology and progression of cancer." (PMID 24369491, 2013). "15p5.33 is a hotspot of genetic predisposition for multiple cancer types, probably because oncogenesis and cell immortalization are closely linked with the telomere maintenance activities of TERT." (PMID 24152305, 2013). "Although TERT mutations have been reported in several cancers, their putative association with distinct biological behavior and clinical or even prognostic characteristics has not been comprehensively studied." (PMID 24174164, 2013). "TERT promoter mutations lead to increased expression of telomerase, which maintains telomere length and genomic stability, thereby allowing cancer cells to continuously divide, avoiding senescence or apoptosis." (PMID 24260374, 2013). "Cancer cell lines and other cancer types also contain these TERT promoter mutations at high frequency." (PMID 24157419, 2013). "It is noteworthy that TERT-CLPTM1L genomic region among Asian population has been linked to increased risk of several cancer types." (PMID 23738012, 2013). "Rs2736098 is located in coding sequence of TERT gene, therefore it has been considered as a putative cancer susceptibility gene." (PMID 24171766, 2013).
cancer (continued). "The association between the TERT rs2736100 single nucleotide polymorphism (SNP) and cancer risk has been studied by many researchers, but the results remain inconclusive." (PMID 22221621, 2012). "In the meta-analysis conducted on 23032 cases and 38274 controls, TERT rs2736100 polymorphism was found to be associated with a significantly increased cancer risk." (PMID 22221621, 2012). "When we investigated the TERT rs2736100 polymorphism and cancer susceptibility, the results suggested that the significance of the pooled ORs was not influenced by any single study in a recessive genetic model." (PMID 22221621, 2012). "A computerized search of PubMed and Embase database for publications on the TERT rs2736100 polymorphism and cancer risk was performed and the genotype data were analyzed in a meta-analysis." (PMID 22221621, 2012). "The overall results of this meta-analysis have shown that the TERT rs2736100 polymorphism is associated with cancer risk." (PMID 22221621, 2012). "In all genetic models, the association between the TERT rs2736100 polymorphism and cancer risk was significant." (PMID 22221621, 2012). "Here, we analyzed pooled data from case-control studies to determine the role of TERT rs2736100 polymorphism in cancer susceptibility." (PMID 22221621, 2012). "A common polymorphism near the telomere maintenance gene TERT has been associated with several cancers, but relationships with other aging traits such as physical capability have not been reported." (PMID 21332924, 2011). "TERT encodes the catalytic subunit of telomerase and activation of telomerase has been implicated in human cell immortalization and cancer cell pathogenesis." (PMID 20628624, 2010). "Additionally, we examined the effects of these treatments on ATP-binding cassette (ABC) transporters, telomerase reverse transcriptase (TERT), and cancer stem cell-related markers as potential mechanisms underlying chemoresistance." (PMID 41860710, 2026). "TERT promoter oncogenic variants have been well documented in human cancers, including HNSCC." (PMID 41489678, 2026). "This dysregulation can involve mutations in the TERT promoter region, epigenetic modifications, or alterations in signaling pathway activity (e.g., in the c-Myc and Wnt/β-catenin pathways), upregulating telomerase activity in cancer cells." (PMID 41301813, 2025). "This suggests that TERT mutations could function as a potential pan-cancer predictive biomarker for ICI therapy." (PMID 40365320, 2025). "The TERT promoter is mutated at high frequencies in multiple cancers affecting adults." (PMID 39760332, 2025). "The TERT promoter regulates telomerase activity, which is highly associated with cancer risk." (PMID 39720865, 2025). "HBV DNA insertional mutagenesis may result in the dysfunction of cancer‐associated genes (e.g., telomerase reverse transcriptase [TERT])." (PMID 39720865, 2025). "TERT also interacts with coactivator 1 α and β to regulate the transcription of mtDNA, which is a critical determinant of cellular metabolism and is closely associated with aging and cancer." (PMID 39871386, 2025). "Non-coding mutations in the TERT promoter, present in 39–74% of BCCs, are associated with telomere shortening and subsequent telomerase activation, a well-established hallmark of numerous human cancers." (PMID 40725190, 2025). "Interestingly, in many cancers, activation of TERT was reported to be frequently due to TERT promoter mutations; subsequently noted to overlap with the TERT promoter G4-forming stretch." (PMID 41026782, 2025). "The evolutionary selection of genetic variants that increase the fraction of the telomerase-encoding TERT-FL isoform might provide this reproductive fitness benefit while decreasing longevity later in life, perhaps due to elevated cancer risk." (PMID 39956830, 2025).
cancer (continued). "Thus, the study uncovers the complex regulation of TERT functions and the contribution of h-TERT germline variants to cancer susceptibility and to telomere biology as well." (PMID 41463021, 2025). "In addition to TERT SNPs, mutations in the promoter of TERT have been detected in over 50 cancer types." (PMID 40244270, 2025). "ATC is a rare malignant tumor, with the most common gene mutation being the TERT promoter mutation." (PMID 39871386, 2025). "However, TERT promoter mutations and dysregulation have been implicated in several cancers, including those of the head and neck." (PMID 40278994, 2025). "TERT SNPs, such as rs2853669, have been linked to an increased risk of cancer." (PMID 40244270, 2025). "Importantly, some of these studies also agree on the need to analyze larger series of carcinomas in advanced stages, aimed at defining the impact that pathogenic alterations of TERT, different from TPM, have on the prognosis of patients." (PMID 40272676, 2025). "In agreement with the theory that considers the molecular alterations involved in TERT re-expression and telomerase activation as events associated with advanced stage, clinically aggressive carcinomas, in our study, TERT amplification was much more frequent in PTCs with DMs." (PMID 40272676, 2025). "The evolutionary selection of genetic variants that increase the ratio of the telomerase-encoding TERT-FL isoform might provide this reproductive fitness benefit while decreasing longevity later in life, perhaps due to elevated cancer risk." (PMID 39802763, 2024). "Elevated levels of telomerase expression, detected in 75-100% of patients, and high telomerase reverse transcriptase (TERT) levels (> 93.8 copies) in cancer tissues have been linked to worse survival compared to cases with low TERT levels (< 93.8 copies; HR, 3.30; 95% CI: 1.98-5.52; p < 0.0001)." (PMID 39439946, 2024). "Recurrent mutations and chromosomal rearrangements in TERT promoters are frequent in human cancers." (PMID 38278800, 2024). "According to previous studies, TERT is a strong risk factor for OS and may promote cancer growth and spread." (PMID 39239547, 2024). "Paradoxically, TERT promoters are hypermethylated in telomerase-positive cancers and hypomethylated in most untransformed cells, suggesting that methylation is associated with telomerase expression in cancer." (PMID 38837897, 2024). "The frequency of TERT promoter mutations may have been high in this study because we assessed only patients with advanced cancer." (PMID 38630010, 2024). "Finally, cancer-specific survival was lower in patients with TERT promoter mutations in encapsulated angioinvasive FTC and widely invasive FTC compared to those without." (PMID 38441247, 2024). "The TERT isoform ratios affect cellular longevity and replicative potential, which can be further modulated by environmental factors, thus contributing to reduced or elevated cancer risk." (PMID 39802763, 2024). "The TERT gene encodes the reverse transcriptase subunit of telomerase and is normally transcriptionally suppressed in differentiated human cells but reactivated in cancers where its expression is frequently associated with poor survival prognosis." (PMID 38859942, 2024).
cancer (continued). "These mutations increase TERT expression, which helps cancer cells grow and survive." (PMID 38667446, 2024). "Finally, variation in both the coding and promoter sequences of TERT has been associated with a variety of cancer types." (PMID 39132489, 2024). "We demonstrated that driver genes (BRAF, RET and TERT, etc.)are co-mutated with other genes, such as DNA damage repair genes and metabolism related genes, thus forming a co-mutation pattern observed more frequently in cancer tissues than benign nodules." (PMID 38886866, 2024). "In addition, we detected a decreased expression of L1 retrotransposons in the TERT+ group, and further decreased L1 expression in promoter mutated TERT+ cancers." (PMID 38859942, 2024). "G228A (Mutation ID: MU832963) and G250 (Mutation ID: MU830690) are the main hotspot mutation of TERT promoter in human cancers and they both reactivates TERT expression by creating a de novo binding site (TTCCGG) for ETS transcription factors, but 90% mutation in HCC are G228A." (PMID 38769666, 2024). "Given the importance of TERT promoter mutations in cancer development and their potential use as a biomarker for clinical outcomes and response to treatment with ICIs, we investigated the distribution of TERT promoter mutations by sex and race across different solid tumors." (PMID 37462445, 2024). "Another mechanism that leads to cancer induces upregulation of the TERT gene aimed to preserve TL which may cause uncontrolled elongation thus making the cells immortal." (PMID 38192544, 2024). "Mutations at two key positions in the TERT promoter are frequent drivers of cancer, but the role of rare, atypical mutations in this region remains unclear." (PMID 39557834, 2024). "Additionally, mutual exclusive analysis of the TERT expression within different cancerous diseases implicated the higher rate of liver hepatocellular carcinoma." (PMID 37884663, 2023). "TERT promoter mutations are known to increase telomerase transcription in many cancers." (PMID 37560909, 2023). "In this review, we summarize diverse molecular mechanisms involved in telomerase activation in cancer cells harbouring TERT promoter mutations, their relationship with disease outcome in patients with different cancer types as well as the importance of anticancer therapies targeting telomerase." (PMID 38033865, 2023). "Moreover, a relatively small number of TERT promoter mutations and wild-type cancers were used in the current study." (PMID 36984536, 2023). "One is a tissue-determined cytodynamic in combination with TERT promoter mutations when cancer stem cells differentiate into mature cancer cells, a phenomenon that would favor TERT reactivation and high expression in tissues with high proliferative/regenerative capacity such as the oral cavity." (PMID 36909826, 2023). "Recently, TERT promoter mutations have been identified in more than 50 types of cancer, suggesting that this mutation may be the most common and earliest occurring genetic abnormality." (PMID 36834592, 2023). "Hence, human telomerase activity or telomerase reverse transcriptase (TERT) is regarded as a diagnostic and therapeutic biomarker in cancer cells." (PMID 38111043, 2023). "The study suggests that targeting TERT promoter (pTERT) mutations may serve as a viable approach for cancer therapy." (PMID 37897649, 2023). "TERT mutations have been correlated to a high neoantigen load in all cancer types." (PMID 37860270, 2023). "Several SNPs in the TERT locus have been associated with cancer risk." (PMID 36980987, 2023). "We call it the “promoter region” because it contains the core TERT promoter, a proximal promoter part containing recognition sites for many transcription factors and a more distant hypermethylation oncological region implicated in cancer progression." (PMID 37511853, 2023).